ALB (albumin)
Diseases named in the same sentence as ALB in open-access papers (continued):
Sharing a sentence is not in itself a finding about the gene and the disease.
brain injury (continued). "Moreover, the results of the SAFE study indicated that resuscitation with 4% albumin might increase mortality in patients with traumatic brain injury." (PMID 25474401, 2014). "In patients with traumatic brain injury, saline and L-HES achieved lower mortality than albumin and balanced crystalloids; especially saline was significantly superior to iso-oncotic albumin (OR 0.55; 95% CI 0.35–0.87)." (PMID 33317590, 2020).
osteoarthritis (23 papers, 2013 to 2025). A noninflammatory degenerative joint disease occurring chiefly in older persons, characterized by degeneration of the articular cartilage, hypertrophy of bone at the margins and changes in the synovial membrane. "Since low albumin levels may be associated with inflammatory conditions or infections, higher albumin levels could indicate the resolution of inflammation, thereby alleviating symptoms of osteoarthritis such as pain." (PMID 38792397, 2024). "Total protein, albumin, complete blood count, and magnesium levels were lower in patients with osteoarthritis." (PMID 35317381, 2021). "The concentration of biological components of synovial fluid (such as albumin, globulin, hyaluronic acid, and lubricin) varies between healthy persons and osteoarthritis (OA) patients." (PMID 27877822, 2015). "The Low Molecular Weight Fraction of 5% human serum Albumin (LMWF-5A) is being investigated as a treatment for knee pain from osteoarthritis." (PMID 24498399, 2014). "Consistently, a recent large NHANES-based study reported that higher neutrophil percentage-to-albumin ratio was positively associated with RA but not with Osteoarthritis, further supporting the relevance of systemic inflammation in RA susceptibility." (PMID 41255642, 2025). "Evidence from a Mendelian randomization (MR) study supports that high levels of retinol and albumin may have a preventive impact on the incidence of osteoarthritis." (PMID 39639939, 2024). "There were significant differences between patients with and without osteoarthritis in terms of albumin (p=0.013), magnesium (p=0.038), total protein (p=0.004), ESR (p=0.047), hemoglobin level (p=0.018), muscle strength (p=0.046), height (p=0.033), and muscle mass (p<0.05)." (PMID 35317381, 2021).
Fever (22 papers, 2011 to 2025). Body temperature elevated above the normal range. "Migration of blood components into surrounding tissues is associated with fever and viremia as well as decreased anion gap, albumin, and lymphocytes levels." (PMID 32485952, 2020). "In the underweight group, PS, number of teeth, and serum albumin value at pre-operation were significantly associated with postoperative fever in univariate analysis, and PS and number of teeth remained significantly associated with postoperative fever in multivariate analysis." (PMID 33081131, 2020). "In which, Linear Predictor = (−1.891) + (−0.177)*Albumin +0.178*Duration of surgery +0.517*ASA classification +0.867*Fever before surgery +2.251*ICU admission +0.534*Total volume of infusion." (PMID 37139371, 2023). "The mean ± 2 SD of albumin levels in the KD group was lower than that in the fever group (3.4 ± 0.4 g/dL vs. 4.0 ± 0.4 g/dL; p < 0.001)." (PMID 35052869, 2022). "Fever was present in 18 (42%), abnormal white blood count in 29 (67%), albumin was less than 3.2 mg/dL in 20 (47%), septic shock in 7 (16%), and ICU admission in 8 (19%)." (PMID 22028704, 2011). "Pyrexia is also an important AE because it can result in decreased albumin." (PMID 34205099, 2021). "In conclusion, we observed in our study that urine WBC and stone size were risk factors of both fever and SIRS, while a high-normal level of serum albumin might be a protective factor of fever." (PMID 28261611, 2017). "The other common ADRs included eosinophilia in eight patients (47.1%); pyrexia in six patients (35.3%); reduced blood albumin and rash in five patients each (29.4%); and ventricular extrasystoles, fatigue and increased blood uric acid in four patients each (23.5%)." (PMID 27928714, 2017). "In the current study, we evaluated the potential risk factors of postoperative complications and observed that urine WBC and stone size were two risk factors for both fever and SIRS, while a high-normal level of serum albumin was the protective factor of postoperative fever." (PMID 28261611, 2017). "Compared to both healthy and fever control groups, the KD group exhibited significantly elevated WBC, NEU, PLT, CRP, ESR, PCT, and ALT, as well as decreased levels of Hb, ALB, and AST (all p < 0.05)." (PMID 40044787, 2025). "The proportions of patients with low hemoglobin and with decreased albumin were both higher in the fever group than those in the no-fever group, suggesting there was a higher disease burden in the fever group." (PMID 30847312, 2019).
focal segmental glomerulosclerosis (22 papers, 2014 to 2026). A renal disorder characterized by sclerotic lesions in the glomeruli. "An increase in urinary albumin and the presence of focal glomerulosclerosis were indicative of progressive damage to the glomerulus." (PMID 35499085, 2022). "Recently, 8,9-EET has been shown to prevent the focal segmental glomerulosclerosis-induced increase in glomerular albumin permeability in vitro." (PMID 25177296, 2014). "Western blotting, immunostaining, and RT‐PCR detected that after 8‐week post ADR injection, all mice developed FSGS by significantly increasing urine albumin excretion, glomerular atrophy, and focal segmental glomerulosclerosis, and a significant loss of podocyte markers podocin and nephrin." (PMID 37749872, 2023). "Glomerular diseases including Diabetic Nephropathy and Focal Segmental Glomerulosclerosis (FSGS) are characterized by podocyte loss, resulting in proteinuria, defined by loss of more than 3 grams of albumin in the urine per 24 h." (PMID 34335284, 2021). "This aligns with KDIGO guidelines, which recognize that patients presenting with nephrotic-range proteinuria while maintaining normal serum albumin levels often indicate the presence of coexistent secondary focal segmental glomerulosclerosis (FSGS)." (PMID 38439903, 2024). "Children with genetic SRNS at disease onset showed a slightly milder initial clinical presentation with less edema and higher serum albumin and a higher proportion of focal segmental glomerulosclerosis than children with nongenetic SRNS." (PMID 41141535, 2025).
fungal infection (22 papers, 2010 to 2025). "Consistently, Our study showed albumin was a risk factor for SGAs usage in patients with DFIs, which usually accompanied by bacteria or fungal infections." (PMID 40873947, 2025). "Low serum albumin levels have been associated with an increased risk of mortality in patients with bloodstream infections because of bacterial or fungal infection." (PMID 39250466, 2024). "Main investigation items were as follows: sex, age, weight, duration of treatment, dosage, department, underlying diseases, risk factors for fungal infection, albumin, liver enzyme, total bilirubin, serum creatinine, estimated glomerular filtration rate." (PMID 35725403, 2022). "The results of this study showed that the APACHE II score and serum albumin levels were two important independent mortality risk factors in ICU fungal infections." (PMID 32795259, 2020). "Primarily, it has to be considered that serum albumin levels are frequently decreased in patients at risk for invasive fungal infections which would increase the active drug concentration." (PMID 24499961, 2014). "A significant correlation was observed in the association of fungal infection with albumin." (PMID 35978737, 2022). "Albumin is abundant in blood and serum albumin level is a prognostic marker for complications in bacteria and fungal infections." (PMID 40873947, 2025). "Serum albumin levels have a prognostic value for complications in viral, bacterial, and fungal infections." (PMID 41209009, 2025). "Peripheral blood lymphocyte and monocyte counts, as well as serum albumin levels, were significantly negatively correlated with fungal infection." (PMID 36237437, 2022). "Upon their admission to ICU, patients who developed fungal infections had lower albumin (3.1 vs. 3.4, p = 0.026) and higher eosinophils (0.03 vs. 0.01, p-0.49)." (PMID 36012869, 2022). "Fungal infection of cornea clearly induce increased expression of alpha 1 antitrypsin, apolipoprotein, haptoglobin, albumin, zinc α 2 glycoprotein (ZAG), lactoferrin, haptoglobin precursor, proteins related to inflammatory events." (PMID 23308132, 2013). "A significant correlation was observed between fungal infection and albumin level." (PMID 35978737, 2022). "Our earlier report and our present results show albumin upregulation in keratitis tear sample indicating that during fungal infection there might be a leakage of this protein from inflamed vessels." (PMID 23308132, 2013). "Many studies have not observed the association between albumin and fungal infections in DFU." (PMID 35978737, 2022). "The results showed that the serum albumin levels and lymphocyte counts were significantly lowered, and the CRP levels were significantly raised after fungal infection." (PMID 36237437, 2022). "Serum albumin levels and leucopenia have prognostic value for complications in viral, bacterial, and fungal infections, and for infectious complications of non-infective chronic conditions." (PMID 38406079, 2024). "Serum albumin levels have prognostic value for complications in viral, bacterial and fungal infections, and for infectious complications of non-infective chronic conditions." (PMID 33925831, 2021). "In addition, this study found that serum albumin as well as lymphocyte and monocyte counts were significantly negatively correlated with fungal infection, whereas the CRP and PCT values showed a significant positive correlation with fungal infection." (PMID 36237437, 2022). "The CAPA group exhibited lower SaO2, PaO2, lymphocyte count, hemoglobin, albumin, and higher lactate, white blood cell count, neutrophil count, NLR, CRP, LDH, D-dimer and NT-proBNP compared to the group without fungal infection." (PMID 38263011, 2024).
hemorrhagic stroke (22 papers, 2008 to 2026). A stroke caused by a bleed on the brain. "Additionally, higher albumin levels were significantly associated with a lower risk of haemorrhagic stroke [HR 0.47 (0.26–0.86), P = 0.01] and all-cause mortality [HR 0.45 (0.35–0.57), P < 0.01]." (PMID 40273298, 2025). "For example, after a hemorrhagic stroke, the concentration of hematin/hemin in hematomas can be extremely high and exceed the local concentration of scavenging proteins such as albumin." (PMID 38534398, 2024). "Compared to the late EN cohort, the early EN cohort had older patients, a higher prevalence of hemorrhagic stroke, a lower prevalence of mechanical ventilation, and lower admission albumin levels." (PMID 39165266, 2024). "Higher serum TA albumin categories were associated with a higher proportion of CVD deaths, as well as CAD and hemorrhagic stroke deaths." (PMID 39385948, 2024). "Because our study was designed to compare ischaemic and haemorrhagic stroke, we studied albumin extravasation in all three models." (PMID 33097782, 2020). "Among hemorrhagic stroke patients, rapid infusion of 50 ml 20% albumin promptly and significantly reversed electroencephalographic abnormalities." (PMID 18318896, 2008). "Nevertheless, in hemolytic disorders, local concentrations of heme derivatives may be significantly higher than albumin concentrations, for instance, in hematoma during hemorrhagic stroke." (PMID 38534398, 2024). "We found only few articles on albumin and hemorrhagic stroke." (PMID 34572977, 2021). "Albumin was found to exert an anticoagulant role and inhibitory effect on platelet function by binding antithrombin, which might aggravate the development of hemorrhagic stroke." (PMID 36814998, 2023). "In conclusion, both the Pan-Immune Inflammation Value (PIV) and the C-reactive protein–albumin–lymphocyte (CALLY) index serve as robust prognostic biomarkers in both ischemic and hemorrhagic strokes by integrating inflammatory, immunological, and nutritional axes." (PMID 41602960, 2026). "Further studies into modulating CAR after the onset of hemorrhagic stroke can be studied to evaluate the utility of modifying CRP and albumin in an inpatient setting, rather than only as a preventative measure." (PMID 33585095, 2021).
pulmonary embolism (22 papers, 2008 to 2026). The obstruction of the pulmonary artery or one of its branches by an embolus, sometimes associated with infarction of the lung. "Platelet-to-albumin ratio fills the gap in the “inflammation-metabolism dimension” of current pulmonary embolism (PE) risk stratification, offering the advantages of low cost and rapid accessibility." (PMID 41210872, 2025). "In multivariate analysis, the RDW-SD was independently associated with pulmonary embolism (OR = 1.188, 95% CI 1.048 to 1.348, p = 0.007) after adjusting for albumin, alanine aminotransferase, aspartate aminotransferase, lactate dehydrogenase, and D-dimer." (PMID 36233510, 2022). "This study preliminarily explored the predictive value of the platelet-to-albumin ratio (PAR) for short-term mortality in patients with pulmonary embolism using machine learning algorithms." (PMID 41210872, 2025). "Lactate dehydrogenase (LDH) and albumin (ALB) were found to be significantly correlated with mortality in pulmonary embolism (PE) patients." (PMID 38962086, 2024). "Apelin, fibulins, haemopexin, a2-macroglobulin, Ig a1-chain C region, TNF-α, HMGB1, neutrophil-to-lymphocyte ratio and albumin are among the other biomarkers whose effectiveness has been investigated in the diagnosis of pulmonary embolism." (PMID 36115957, 2022). "Based on univariate analyses, six parameters were identified as significant predictors of pulmonary embolism (PE) and were selected for the construction of the Hema-PE Score: D-dimer/albumin ratio, immobility, central venous catheter, C-reactive protein (CRP), platelet count, and hemoglobin." (PMID 41156207, 2025). "The present study suggests that the D-dimer/albumin ratio may represent a useful biomarker, and that the newly developed Hema-PE Score shows promising predictive performance for pulmonary embolism in patients with hematologic malignancies." (PMID 41156207, 2025). "Lung perfusion using 99mTc-macroaggregated albumin single-photon emission computed tomography (SPECT) and lung computed tomography (CT) is a useful modality for identifying patients with pulmonary artery embolism." (PMID 36424511, 2022).
vasculitis (22 papers, 2014 to 2025). "Managing this patient requires addressing not only the vasculitis but also the substance abuse and nutritional deficiencies, including low albumin, that impair wound healing." (PMID 40951243, 2025). "The presumed mechanism for intestinal albumin loss is the increase in permeability resulting from vasculitis of the small vessels." (PMID 27287396, 2016). "The decrease of ALB may be related to the extravasation of ALB caused by vasculitis, the consumption of ALB by acute infection and the influence of liver ALB synthesis." (PMID 40338980, 2025). "CRP, ESR, fibrinogen, d-dimers, albumin and hemoglobin in the peripheral blood correlate well with the activity of vasculitis and identify severe patients." (PMID 34445984, 2021). "Patients with active vasculitis were characterized by a lower concentration of hemoglobin and albumin in the peripheral blood compared to the control group and the evaluation performed in remission." (PMID 34445984, 2021). "Compared to survivors, the death group exhibited a higher smoking index, lower serum albumin levels, higher serum C-reactive protein levels, higher Birmingham Vasculitis Activity Score (BVAS), higher Five-Factor Score, and a more severe European Vasculitis Study Group (EUVAS) categorization system." (PMID 37986108, 2023). "Disease duration, ethnicity, negative anti-La, albumin and low renal disease activity are all associated with NA but not NN, whereas hydroxychloroquine and high vasculitis disease activity are associated with NN but not NA." (PMID 24502558, 2014). "Surviving patients had less severe vasculitis (lower BVAS), less severe kidney disease (lower creatinine and hematuria, and fewer needed dialysis at presentation) and higher serum albumin levels." (PMID 26123651, 2015). "Additionally, following a month of monitoring, anti-C5aR antibody levels showed a positive correlation with total protein levels in the FSGS group and a negative correlation with albumin levels in the c-ANCA vasculitis group." (PMID 40943842, 2025). "However, a significant correlation was found with albumin in UC.Whether this decrease in both albumin and ERL density indicates a component of vascular leak inthe setting of vasculitis is unclear." (PMID 34805987, 2021).